TLK2 (tousled like kinase 2)
Diseases named in the same sentence as TLK2 in open-access papers (continued):
Sharing a sentence is not in itself a finding about the gene and the disease.
cancer (21 papers, 2012 to 2026). A tumor composed of atypical neoplastic, often pleomorphic cells that invade other tissues. "In a broader analysis across multiple cancers, high expression of TLK1 or TLK2 was significantly associated with poor prognosis in most of cancer types with wild-type BRCA1 (or low TLK1 associated with good outcome), but this was not seen in tumors with BRCA1 deficiency." (PMID 39844055, 2025). "Additionally, TLK2 deregulation has been linked to cancer in multiple studies." (PMID 30655559, 2019). "TLK2 haploinsufficiency causes distinct neurodevelopmental disorders, and TLK upregulation drives cancer cell proliferation." (PMID 41507136, 2026). "In conclusion, the genetic status and expression levels of TLK1 and TLK2 should be investigated as potential biomarkers for predicting resistance or sensitivity to PARPi therapy in cancers with HRD." (PMID 39844055, 2025). "There are ongoing efforts to develop TLK1 and TLK2 inhibitors for targeting cancer cells with their promising roles in maintaining genome stability." (PMID 39727191, 2025). "Here, we found that TLK2 mRNA is abnormally expressed in pan-cancer, with notable implications for prognosis in specific tumors, particularly in LIHC." (PMID 38343446, 2023). "GNL1 (Guanine nucleotide binding protein like 1) promotes cancer cell proliferation by modulating G1/S and G2/M phase transition, while TLK2 (Tousled‐like kinases 2) is important in chromatin assembly and maintenance of replication fork integrity." (PMID 36775869, 2023). "TLK2 depletion activates the cGAS–STRING–TBK1 innate immune axis, and a high TLK2 level contributes to immune evasion of cancers positive for alternative lengthening of telomeres." (PMID 36134026, 2022). "At the same time, amplification of TLK2 plays a crucial role in the development of cancers and is correlated with poor prognosis." (PMID 36134026, 2022). "Our analysis of the amplified cancer genes also identified probable drivers TLK2 and IL6, whose amplification and/overexpression have been implicated in genomic instability and Jak/Stat activation, respectively." (PMID 34313788, 2021). "TCI identified 6 such SGA-FIs, including some well-known cancer drivers, such as PTEN and NEFH, and potential cancer drivers mentioned in recent studies, such as TLK2, USP13, and PIM3." (PMID 31276486, 2019). "Emerging evidence demonstrated that TLK1 and TLK2 are involved in cancer progression and therapeutic resistance and it has been shown that inhibition of TLK potentiates cell-killing in different types of cancers, making TLK1 and 2 attractive targets for therapeutic strategy development." (PMID 39727191, 2025). "As expression of TLK1 and TLK2 exhibited significantly different patterns across cancer types, this emphasizes the need to consider the distinct genetic statuses and activities of TLK1 and TLK2 based on the cancer subtype for their application in therapeutic strategies." (PMID 39844055, 2025). "Using the TIMER database, we observed varying TLK2 expression levels in different cancer types." (PMID 38343446, 2023). "Our finding that SCFFBXL3+CRY1/2 enhances turnover of TLK2 suggests another mechanistic link by which deregulation of clock components could lead to a cancer-prone phenotype." (PMID 30655559, 2019). "Most, if not all, of the reports about the function of TLKs focus on the study of TLK1, while the function of TLK2 and its role in human cancers are still largely unknown." (PMID 27694828, 2016). "Copy-number amplification of TLK2 has been correlated with overexpression in several other cancers." (PMID 22291905, 2012). "Among the inferred targets are tousled-like kinase 2 (TLK2) and the deubiquitinating enzyme ubiquitin-specific-processing protease 7 (USP7) whose overexpression correlates with poor survival in cancers." (PMID 26427375, 2015). "It is upregulated in cancers, driving tumour growth, however, the role of TLK2 in postmitotic neurons is not understood." (PMID 42023051, 2026).
cancer (continued). "Since TLK1 and TLK2 have higher sequence similarity and function similarly, we hypothesized that TLK1 may also play role in the dissemination of the cancer cells." (PMID 35064619, 2022). "The top amplified cancer genes were KRAS, CDK4, BRAF, IL6, TLK2 and MITF." (PMID 34313788, 2021). "By contrast, TLK2 and IL6 have not been reported as an amplification driver in either the Cancer Gene Census or OncoKB and they are amplified in 1–2% of the TCGA cohort." (PMID 34313788, 2021). "Notably, TLK2 expression did not exhibit the same correlation with the DepMap score, suggesting that TLK1 and TLK2 may have differential effects on cellular sensitivity to PARP disruption in the context of BRCA1 deficiency, and that these effects may be cancer type- and context-dependent." (PMID 39844055, 2025).
tumor (11 papers, 2012 to 2026). "While the tumours in the combined treatment group still re-grew after 70 days of treatment, this could be attributable to the loss of TLK2 inhibition as suggested by the western blot analysis of tumours harvested at the end of the treatments." (PMID 27694828, 2016). "Additionally, we found that TLK2 expression was significantly positively associated with several key molecules of tumor-related signaling pathways (i.e., cell cycle control, WNT/beta-catenin signaling, AKT/m-TOR/MAPK signaling, and oxidative stress) in the TCGA LIHC dataset." (PMID 38343446, 2023). "TLK2 is not only required for normal development and maintenance of genome stability but is also closely related to the tumor." (PMID 38343446, 2023). "TLK2 silencing by shRNA suppressed tumor proliferation and invasion in vitro and in xenograft studies." (PMID 32408897, 2020). "Our result showed that TLK2 inhibition alone or in combination with tamoxifen substantially inhibited the growth of MCF7 xenograft tumours." (PMID 27694828, 2016). "Gene expression data show that TLK2 expression is primarily upregulated by copy-number increase at this locus (R=0.81), and correlates with increased tumour stage." (PMID 27694828, 2016). "As shown by the study of a preclinical xenograft tumour model, TLK2 inhibition significantly improved progression-free survival." (PMID 27694828, 2016). "Additionally, we assessed TLK2 expression in tumor tissues and matched-adjacent normal tissues using TCGA data." (PMID 38343446, 2023). "Alternatively, the microenvironment of the primary tumours may provide additional signalling required for the action of endogenous TLK2." (PMID 27694828, 2016). "The results suggest that TLK2 expression might affect some tumor-related signaling pathways." (PMID 38343446, 2023). "The corresponding tumor arraylet describes a global pattern of tumor-exclusive co-occurring CNAs, including most known GBM-associated changes in chromosome numbers and focal CNAs, as well as several previously unreported CNAs, including the biochemically putative drug target-encoding TLK2." (PMID 22291905, 2012). "Within genomic regions highly susceptible to oestrogen receptor alpha (ERɑ)-related chromothripsis, a subgroup of genes, including Tousled-Like Kinase 2 (TLK2), has been identified as upregulated in tumours exhibiting chromothripsis." (PMID 39190283, 2024). "TLK2 overexpression means a higher level of AFP and ALBI score, worse MVI grade and TNM stage, larger tumor diameter, and greater tumor number in HBV-related HCC patients." (PMID 38343446, 2023). "The resulting overexpression of TLK2 is more significant in aggressive and advanced tumours, and correlates with worse clinical outcome regardless of endocrine therapy." (PMID 27694828, 2016). "They showed that four tumor-specific mRNA (ALOX5, RBL2, VEGFA, TLK2) present in EVs (defined as present in tumor-derived-, urine- and plasma-EVs, but absent in tumor-adjacent tissue EVs) may be used as RCC biomarkers in the future." (PMID 35629194, 2022). "Therefore, it is possible that TLK2 acts as a context-dependent driver of ER-positive/luminal tumours in the absence of PIK3CA expression." (PMID 26427375, 2015). "Interestingly, TLK2 overexpression can co-occur with PTEN loss or when PIK3CA, a key driver of ER-positive/luminal tumours, is not overexpressed." (PMID 26427375, 2015).
neurodevelopmental disorder (4 papers, 2018 to 2026). A behavioral and cognitive disorder with onset during the developmental period that involves impaired or aberrant development of intellectual, motor, or social functions. "One study described a patient with a homozygous TLK2 variant, leading to an autosomal recessive severe neurodevelopmental disorder." (PMID 39296544, 2024). "Totally, 39 TLK2 gene variants in 49 patients were reported to exhibit TLK2-related neurodevelopmental disorders in four studies." (PMID 39296544, 2024). "Tousled-like kinase 2 (TLK2) gene variant-related neurodevelopmental disorder was recently described." (PMID 39296544, 2024). "In summary, here we describe a patient with a homozygous TLK2 variant leading to an autosomal recessive severe neurodevelopmental disorder, highlighting that certain TLK2 variants can cause a recessive disease, as the heterozygous parents were healthy." (PMID 31558842, 2020). "In conclusion, we show that both de novo and inherited mutations in TLK2 cause a distinct neurodevelopmental disorder, hallmarked by mild developmental delay, a variety of behavioral disorders, severe gastro-intestinal problems, and facial dysmorphism." (PMID 29861108, 2018). "This study also expanded the genotype profile of the newly defined TLK2-related neurodevelopmental disorder." (PMID 39296544, 2024). "Here, we presented a Chinese family with TLK2-related neurodevelopmental disorder." (PMID 39296544, 2024).
TLK2 also shares sentences with these, for which no sentence is quoted: breast adenocarcinoma (2 papers); neurological disorders (2); acute myeloid leukemia (1); adenocarcinoma (1); adenoid cystic breast carcinoma (1); bladder urothelial carcinoma (1); cholangiocarcinoma (1); dermatofibrosarcoma protuberans (1); developmental delay (1); esophageal carcinoma (1); head and neck squamous cell carcinoma (1); hepatocellular carcinoma (1); infection (1); infectious disease (1); invasive breast carcinoma (1); kidney chromophobe (1); lung adenocarcinoma (1); lung squamous cell carcinoma (1); microcephaly (1); Parkinson disease (1); schizophrenia (1); squamous cell carcinoma (1); stomach adenocarcinoma (1); thymoma (1); thyroid carcinoma (1); uterine corpus endometrial carcinoma (1).